CD4 (CD4 molecule)
Diseases named in the same sentence as CD4 in open-access papers (continued):
Sharing a sentence is not in itself a finding about the gene and the disease.
myeloma (continued). "Comparison of the skewed CDR3-size lengths of CD4 or CD8 T cells isolated from splenocytes of B10.D2 mice sensitized with myeloma or Balb/cJ cells, compared to non-sensitized B10.D2 control mice (skewed if mean peak area> mean+3SD of corresponding control peak)." (PMID 25415267, 2014). "As a consequence, multiple myeloma cells showed expression of HLA-DR with no methylation in CIITA-PIV, perhaps making them a good target for CD4+ T-cells, which recognise antigen restricted by MHC class II molecules." (PMID 14970863, 2004).
syphilis (151 papers, 2004 to 2026). A contagious bacterial infection caused by the spirochete Treponema pallidum. "Higher baseline CD4+ T cell counts were associated with increased risks of syphilis and HPV, whereas HSV-2 incidence was more common in older or immunocompromised individuals." (PMID 42221463, 2026). "Among the infectious dermatoses, oral candidiasis (P=.001), syphilis (P=.002), and condyloma acuminatum (P=.03) showed statistically significant associations with the CD4 count (<200 cells/mm3)." (PMID 37581910, 2023). "If an HIV-positive person becomes infected with syphilis, the acquired bacterial infection can cause a transitory reduction or even a permanent loss of CD4+ T cells and can increase the viral load." (PMID 36986278, 2023). "In a study of 84 PWH, of which 80% were on suppressive ART, early syphilis was associated with a significant reduction in the total lymphocyte level and levels of lymphocyte subsets including CD4 + T cells." (PMID 36587188, 2022). "Intriguingly, a higher CD4/CD8 ratio before syphilis was associated with positive change, and hence less decline in CD8 + T-cell and total lymphocyte levels." (PMID 36587188, 2022). "Even though our study is not designed to verify the link between syphilis, HIV viral load and CD4 cell count, our data support the idea of a strict monitoring among high-risk subjects, as those with a known history of syphilis." (PMID 35587482, 2022). "Rapid diagnostic tests for HIV and syphilis diagnosis and liver function testing as well as point-of-care technologies for CD4, HIV nucleic acid (viral load and early infant diagnosis), creatinine, and hemoglobin testing exist, with more in development." (PMID 31048881, 2019). "ART attrition was associated with syphilis diagnosis (hazard ratio (HR): 2.23; CI: 1.35–3.68) and CD4 <50 cells/μL (HR: 1.88; CI: 1.15–3.06)." (PMID 27389256, 2016). "Younger age, history of syphilis infection at baseline, positive anti-Eh, and higher baseline CD4 count were identified as risk factors for incident syphilis." (PMID 27992604, 2016). "Although numerous studies on ocular syphilis have been reported, there are limited data about HIV-related risk factors such as HIV viral load or CD4+ cell count as they relate to syphilis serology and CSF laboratory findings." (PMID 26297110, 2015). "LSR was associated with an older age, late syphilis, lower nadir CD4+ and detectable HIV viral load." (PMID 25394158, 2014). "Furthermore, a modest decrease in CD4+ T-cell count (approximately −30/μL) was observed during the syphilis episode, which was independently associated with an increase in HIV RNA levels." (PMID 39941295, 2025). "The genital ulcers caused by syphilis may stimulate the recruitment of antigen-presenting cells and CD4+ T cells at the lesion site; spirochetes also induce the expression of CCR5 in macrophages." (PMID 36986278, 2023). "In conclusion, our findings demonstrate for the first time that neurological progression in syphilis patients is associated with increased circulating Tregs and CSF CD4+ T cells and reduced local Treg response is implicated in the development of symptoms in neurosyphilis patients." (PMID 24244772, 2013). "Moreover, CD4 count <500 cells/mm3 was also a risk for acquiring active syphilis (AOR = 2.45, 95%CI = 1.51, 11.71), which could be explained by syphilis reactivation as immunosuppression." (PMID 37498806, 2023). "In 22 patients who had HIV/syphilis coinfection detected by using the traditional algorithm, the mean CD4+ and mean CD8+ T-lymphocyte values were 579.6 and 956.9 cells/μL, respectively." (PMID 39941295, 2025). "Forty-nine (25.8 %) episodes occurred in patients who had CD4 count < 350 cells/mm3 at syphilis diagnosis." (PMID 40157281, 2025). "Other limitations of the dataset include the self-reported syphilis history and incomplete data on CD4 count, viral load, and antiretroviral therapy for PLWH." (PMID 39946129, 2025).
syphilis (continued). "Schöfer and coworkers compared the mean CD4 counts of 44 HIV-infected syphilis patients with typical maculopapular rashes versus 11 patients with UNRS." (PMID 38920894, 2024). "Treg cells, as a vital subset of CD4+T cells, played a crucial role in inhibiting the host immune response during early syphilis." (PMID 38694502, 2024). "A robust delayed-type hypersensitivity (DTH) response, mediated by CD4 cells, is crucial to the control of syphilis." (PMID 38920894, 2024). "In our cohort, incident histologic anal HSIL was associated with baseline syphilis status, anal high‐risk HPV infection and CD4 count." (PMID 38695517, 2024). "TPA-specific reactive CD4+ T-helper cells were detectable in blood and skin of syphilis patients at the time of initial presentation and persisted for as long as 10 years following treatment." (PMID 39147388, 2024). "Specificity of RDTs was similar in the stratified analysis by age, sex, time since HIV diagnosis, ART, CD4 cells count, viral load, history of syphilis, RPR titers, operator, and re-training." (PMID 36893095, 2023). "Among the infectious dermatoses, oral candidiasis (P=.001), syphilis (P=.002), and condyloma acuminatum (P=.03) showed statistically significant correlations with CD4 cell counts." (PMID 37581910, 2023). "Decreases in CD4 cell counts were substantially correlated with oral candidiasis, syphilis, and condyloma acuminatum." (PMID 37581910, 2023). "While plasma HIV-1 RNA level was unaffected by syphilis in that study, higher risk of plasma HIV-1 RNA elevation and decline of CD4 + T-cell level were observed in another study with participants receiving ART." (PMID 36587188, 2022). "The coinfection of syphilis with HIV has been linked to more severe clinical presentations increased risk of neurosyphilis, decreased CD4+ count, and an interesting phenomenon of overlapping primary and secondary syphilis." (PMID 36845243, 2022). "When stratified by CD4 + T cell count, we found that syphilis prevalence among PLWH decreased as CD4 + T cell count increased." (PMID 36324449, 2022). "A recent report described the potential role of syphilis in inducing apoptosis and pyrotosis in CD4 + and CD8 + T-lymphocytes by altering the intracellular expression of caspase-1 and caspase-3 and their levels in the circulation." (PMID 36587188, 2022). "In the multivariable analysis,only pre-syphilis CD4/CD8 ratio was independently associated with increases in CD8+T-cell (p=0.014) and total lymphocyte levels (p=0.039) during syphilis." (PMID 36587188, 2022). "Syphilis and HIV co-infection can pose considerable health burdens to HIV-positive MSM because syphilis can elevate HIV viral load and decreases CD4 count in HIV-positive patients, thus increasing the risk of HIV-transmission to their serodiscordant partners." (PMID 36438237, 2022). "In this retrospective study with PWH on suppressive ART, CD4 + T-cell level declined after incident syphilis and recovered after successful syphilis treatment." (PMID 36587188, 2022). "The final aim was to identify HIV- and syphilis-related determinants of CD4 + and CD8 + T-cell count and total lymphocyte level." (PMID 36587188, 2022). "As expected women who initiated ART pre-conception had the lowest median CD4 cell count and highest rates of TB and syphilis in our study population." (PMID 36474212, 2022). "Pre-syphilis CD4/CD8 ratiowas associated with increases in CD8+ T-cell (p=0.001) and total lymphocytelevels (p=0.046) during syphilis." (PMID 36587188, 2022). "In the subgroup analysis of CD4 + T cell count, we found that the lower the CD4 + T cell count, the higher the prevalence of syphilis among PLWH." (PMID 36324449, 2022). "In PWH on suppressive ART, incident syphilis leads to a transient decline in CD4 + T-lymphocyte level." (PMID 36587188, 2022). "Of the included clients, 46.0% were born after EPI, 25.9% had a CD4 count of less than 200 cells/mm3, and 19.3% had syphilis diagnosed at baseline." (PMID 35057784, 2022).
syphilis (continued). "Current European guidelines suggest considering CSF examination in asymptomatic PLWH with late syphilis and CD4+ T cells ≤350/ul or a serum Venereal Disease Research Laboratory (VDRL) or RPR titer >1:32." (PMID 34255767, 2021). "Kaplan-Meier analysis indicated that HIV-infected MSM with syphilis testing achieved CD4+ cell count >350 cells/mm3 significantly earlier than the patients without syphilis testing." (PMID 34307399, 2021). "Screening for syphilis should be done for all HIV patients given the high prevalence of the infection and the risk that aggressive forms of neurosyphilis can occur despite recovery of CD4+ T cell counts in untreated syphilis." (PMID 33276749, 2020). "Asymptomatic or undiagnosed syphilis negatively impacts HIV prognoses by reducing CD4 counts and increasing viral loads making early syphilis detection important when delivering HIV care." (PMID 29534681, 2018). "Baseline laboratory tests (creatinine/ALT/syphilis/HBsAg/anti‐HCV/CD4/CrAg if CD4 < 100) and chest x‐ray were performed according to national guidelines." (PMID 30051631, 2018). "On the univariate regression analysis younger age, higher CD4 cell count, HCV exposure intervals which occurred before virologically suppression, and peri-incident syphilis were associated with an increased hazards ratio for HCV acquisition." (PMID 28253838, 2017). "Regardless of the HPV vaccination status, the vaccine HPV-16/18 strains were significantly more prevalent among young women of advanced secondary education, those who tested positive for other STIs (HIV and syphilis) and those with CD4 count <500 cells/ μL." (PMID 27482705, 2016). "Two of them were found to be seropositive for syphilis, two for hepatitis B and one for hepatitis C. The estimated mean CD4 count was 341.1 ± 237.4/mm3." (PMID 27759759, 2016). "After implementation of point-of-care testing, there was no significant change in uptake of overall hemoglobin screening (67.9% to 83.0%; p = 0.229), syphilis screening (80.8% to 87.0%; p = 0.282) and CD4+ T-cell testing (84.9% to 83.5%; p = 0.930)." (PMID 26308345, 2015). "Syphilis diagnosis was less common among Indigenous men, men with higher CD4 cell counts, and, for first diagnoses only, among men with less than high school education." (PMID 26289937, 2015). "Out of 1013 HIV–infected patients approached during the study period, 21 (2.1%) were excluded because 2 patients took syphilis treatment, 1 refused to participate, 3 were children aged < 15 years, and 15 had CD4+ T–cell count ≤ 50 cells/μl." (PMID 25884178, 2015). "A consecutive 993 HIV–infected participants were studied; but individuals under 15 years of age or treated for syphilis or those with a CD4+ T–cell count below 50 cells/μl were excluded." (PMID 25884178, 2015). "Nevertheless, men with high CD4 cell counts had lower syphilis diagnosis rates; this could be a marker for better overall health, differences in sexual behaviours and networks, or alternatively may be explained by reverse causation, as CD4 decline has been noted following syphilis acquisition." (PMID 26289937, 2015). "This study reveals that while POC tests for hemoglobin, syphilis, and CD4+ T-cell counts can greatly improve the delivery of ANC services, having access to these technologies does not mean that this potential is realized." (PMID 26308345, 2015). "The factors significantly associated with CE were alcohol consumption, HIV infection, CD4 cell count, history of HAART, HCV infection, syphilis, and use of corticosteroids, NSAIDs, acetaminophen, or PPIs." (PMID 26208220, 2015). "Of note, more than half (57.8%) of the patients had secondary syphilis at enrollment, 64% had baseline CD4 cell counts of more than 350 cells/μl, and 35.4% had a prior history of syphilis." (PMID 25286091, 2014). "A repeat CD4 count and HIV-l load at the end of his syphilis treatment were 785 CD4 cell/μL and 792 copies/mL, respectively." (PMID 25349616, 2014).
syphilis (continued). "This study found an increase in HIV-1 RNA levels and a reduction in CD4 cell counts among those with an initial CD4 count of >500 cells/μL, which improved after the treatment of syphilis." (PMID 26316953, 2013). "Different studies in HIV-infected patients with syphilis have reported a transient decrease in CD4+ cell count and an increase in VL." (PMID 26316966, 2013). "Mean CD4 counts were lower during syphilis than before (496 versus 590 cells/μL, P < 0.001) and increased after treatment (597 versus 509 cells/μL, P < 0.001)." (PMID 26316953, 2013). "HIV-infected patients with baseline RPR titer ≤1:16, syphilis history, and/or a CD4 T-cell count <350 cells/ml should be closely monitored for serologic failure after early syphilis treatment." (PMID 24369955, 2013). "Initial studies focused on the effect of syphilis coinfection on CD4 cell counts and HIV-1 RNA plasma levels." (PMID 26316953, 2013). "In conclusion, HIV-infected patients with baseline RPR titer ≤ 1:16, syphilis history, and/or a CD4 T-cell count <350 cells/ml should be closely monitored for serological failure after early syphilis treatment." (PMID 24369955, 2013). "It is conceivable that IL-17 producing T-cells play an important compensatory role in SS, particularly in HIV-syphilis co-infected patients with very low CD4+ T-cell counts." (PMID 22816000, 2012). "KAIS was a nationally representative sero-survey that included demographic and behavioral indicators and testing for HIV, HSV-2, syphilis, and CD4 cell counts in the population aged 15–64 years." (PMID 22574226, 2012). "KAIS was a nationally representative population-based sero-survey that examined demographic and behavioral indicators and serologic testing for HIV, HSV-2, syphilis, and CD4 cell counts in 15,853 consenting adults aged 15–64 years." (PMID 21423615, 2011). "Syphilis screen, ELISA or Western blot test, complete blood count, CD4 cell count, plasma viral load." (PMID 23198102, 2011). "All 30 women in the study with GUD were also HSV-2-seropositive and had similar STI history, syphilis prevalence, baseline CD4 counts and HIV-1 log10 viral loads when compared to women without GUD." (PMID 21637835, 2011). "Bivariate analysis additionally showed a correlation between clustering and syphilis (p < 0.001), higher CD4 counts (p = 0.002), Chlamydia infection (p = 0.013) and primary HIV (p = 0.017)." (PMID 20822507, 2010). "Ulcers resulting from syphilis infection might increase HIV transmission, and syphilis might increase HIV viral load and reduce CD4+ T-cell count, which might cause faster HIV progression and treatment failure." (PMID 39941295, 2025). "Syphilis causes both increased concentrations of HIV in blood plasma and decreased CD4+ cells." (PMID 41295583, 2025). "Although there are studies suggesting that syphilis may increase viral load levels and decrease CD4+ T lymphocytes, the data are contradictory." (PMID 39065024, 2024). "We also found that uncontrolled viremia, and not a low CD4 count, is a major risk factor for ulceronodular-rupioid syphilis in HIV patients." (PMID 38920894, 2024). "These high proportions of rare manifestations may be due to the high prevalence of HIV and syphilis coinfection, or reflect an ineffective immune response to syphilis, despite the vast majority of these patients having normal CD4+ cell counts." (PMID 38292581, 2024). "The pathogenesis of UNRS in HIV patients may differ from the typical maculopapular rash of secondary syphilis in an immunocompetent person because CD4 T-cell depletion leads to increased tissue infiltration and activation of cytotoxic T cells and neutrophils." (PMID 38920894, 2024). "Of the participants who tested positive for syphilis, 53.1% had CD4 counts of ≤ 499 cells/μL." (PMID 38962784, 2024). "In patients with HIV, primary or secondary syphilis may also cause a transient decrease in CD4 cell count and an increase in HIV viral load that improves with syphilis treatment." (PMID 39268262, 2024).